IL21 (interleukin 21)
Diseases named in the same sentence as IL21 in open-access papers (continued):
Sharing a sentence is not in itself a finding about the gene and the disease.
immune diseases (13 papers, 2008 to 2025). "A previous study has shown that interleukin-21 (IL-21) treatment restores not only the Th17 cells in the gut mucosa, but also dramatically reduces immune dysfunction in rhesus macaques." (PMID 27379092, 2016). "Moreover, IL-21 is well known to be related to immune diseases and regulates the differentiation of CD4+ T-cells." (PMID 32684837, 2020). "Genetic variants near IL21 confer risk of immune diseases, and allergic sensitisation, but are not in LD with our mosquito trait loci." (PMID 28199695, 2017). "Altogether, our data indicate elevated contents of inflammatory cytokines TNF-α, IL-4, IL-21, BAFF, IL-31, IL-5 and APRIL in CSF samples from ASD patients, suggesting the potential inflammatory conditions and immune dysfunctions that might contribute the pathogenesis and progression of this disease." (PMID 38114596, 2023).
bacterial infections (8 papers, 2017 to 2025). "Although the IL-17 cytokine family is associated with cells of the adaptive arm of the immune system, in bacterial infections such as those caused by P. aeruginosa, innate immune cells are the first responders in secretion of IL-17, IL-21, IL-22, and IL-23." (PMID 28680858, 2017). "Collectively, these findings highlight the importance of IL-21 in mounting immune defense against bacterial infections." (PMID 37759501, 2023). "Collectively, the results indicate that IL-21 plays an important role in regulating the intestinal inflammation induced by bacterial infection in grass carp." (PMID 37759501, 2023). "Our findings shed light on the functions of IL-21 in regulating the intestinal immunity of bony fish during bacterial infection." (PMID 37759501, 2023). "Our results suggest that IL-21 plays an important role in regulating intestinal inflammation induced by bacterial infection." (PMID 37759501, 2023). "The results demonstrate that IL-21 is involved in regulating the intestinal inflammation induced by bacterial infection in grass carp." (PMID 37759501, 2023). "Previous studies have shown that fish il21 genes are expressed mainly in the head kidney, spleen and mucosal tissues including gills and intestines, and are inducible in response to immune stimuli and bacterial infections." (PMID 37759501, 2023). "Taken together, these observations indicate that il21 is activated during bacterial infection." (PMID 37759501, 2023). "Bacterial infections, as an environmental factor in MS pathogenesis play role in T helper 17(Th17) increase and it enhancing the production of pro-inflammatory cytokines such as Interlukin-21(IL-21), IL-17 and IL -22." (PMID 34847159, 2021). "IL-21 can have both pro-inflammatory or anti-inflammatory functional roles, depending on the cellular context and cytokine milieu, but our current findings importantly extend the known actions of IL-21, particularly related to neutrophil biology and bacterial infection." (PMID 30969166, 2019).
infectious disease (7 papers, 2010 to 2023). A disorder directly resulting from the presence and activity of a microbial, viral, or parasitic agent in humans. "Several studies have shown that genetic variations in Th17 pathway genes (including IF-17A, IF-17F, IL-21, and IL-23R) are associated with infectious disease susceptibility and clinical manifestations." (PMID 36483566, 2022). "IL-21 action is associated with immune injury and viral replication in infectious diseases." (PMID 37875903, 2023). "In infectious disease models, particularly chronic viral infections, IL-21 produced by CD4 T has emerged as an important modulator of CD8 T cell resident memory and exhausted cells development, homeostasis, and function." (PMID 35648273, 2022). "Recently, genetic adjuvants using the cytokines with the synergy of IL-21 and IL-15 have been demonstrated to induce enhanced protective immunity in animal models against infectious disease." (PMID 25192845, 2014). "Similar to adjuvants including IL-12, IL-18 and IL-15, the addition of cytokine genes combined with IL-21 and IL-15 can facilitate the efficacy of potential DNA vaccines against infectious disease." (PMID 25192845, 2014). "Together, the role for IL-21 in the homeostatic balance of T and B cell development in the context of infectious diseases appears to be important and remains to be fully elucidated." (PMID 23516660, 2013). "Previous studies have analyzed the association between IL-21 gene variation and the risk of infectious diseases, but its role in PTB has not been explored." (PMID 36483566, 2022). "Thus, type I IFNs should be added to the long list of cytokines (IL-1β, IL-4, IL-6, IL-15, IL-21) and members of the tumor necrosis factor superfamily (TNFSF) (GITR-L, 4-1BB-L, OX40-L and TNF-α) that are purported to decrease Treg suppressive function in autoimmune and infectious disease models." (PMID 29672594, 2018).
inflammation (5 papers, 2017 to 2025). Aberrant reaction of the microcirculation characterized by movement of fluid and leukocytes from the blood into extravascular tissues. "At the same time, treatment with recombinant IL-21 provided Dock8 KO mice with marked protection from OVA-induced airway inflammation, accompanied by alleviation of inflammatory infiltration." (PMID 34867940, 2021). "Pathogenic Th17 cells secrete pro-inflammatory cytokines, such as IL-21, which play pivotal roles in the synovial inflammation." (PMID 28569167, 2017).
renal disease (4 papers, 2011 to 2025). "Similarly, in the murine BXSB-Yaa model of SLE, splenic ICOS+ CD4+ T cell production of IL-21 was linked to renal disease and early mortality." (PMID 27559335, 2016). "A study of the mRNA-1273 vaccine-induced SARS-CoV-2-specific memory T-cell response revealed an increase in IL-21 expression in memory T cells in patients with kidney disease." (PMID 40070834, 2025). "Tph cells can secrete interleukin-21 (IL-21), interferon (IFN) and C-X-C motif chemokine ligand 13 (CXCL13) to moderate renal disease." (PMID 39390361, 2024).
cerebral artery (3 papers, 2015 to 2022). "Both IL-21 and CD40L have been linked to colorectal tumorigenesis." (PMID 26397137, 2015).
colon (2 papers, 2015 to 2022). "Moreover, IL-21 did not affect proliferation and survival of such cells, thus arguing against a role for this cytokine in directly modulating malignant cell growth in colon carcinogenesis." (PMID 25839161, 2015).
hematological malignancies (1 paper, 2024). "To determine whether IL-21 also sensitizes LPSCs to cell-based therapies currently used in hematological malignancies, we treated LPSCs from two newly diagnosed patients with AML with CAR T cells targeting the AML surface antigen CD70 in the presence and absence of rh-IL-21." (PMID 39536753, 2024).
metabolic disease (1 paper, 2016). A congenital disorder (due to inherited enzyme abnormality) or acquired (due to failure of a metabolically important organ) disorder resulting from an abnormal metabolic process. "In obese subjects it has been demonstrated that IL-21 responsive cells are accumulated in adipose tissue where they are hypothesized to contribute to the metabolic disease progression by fuelling the inflammatory pathways." (PMID 27095356, 2016).
neurodegenerative disease (1 paper, 2020). A disorder of the central nervous system characterized by gradual and progressive loss of neural tissue and neurologic function. "A potential proinflammatory role of IL-21 in auto-immune and neurodegenerative diseases has been discussed." (PMID 32185190, 2020).
overlap syndrome (1 paper, 2025). "Additionally, IL-21 assists IL-23 and TGF-β in Th17 differentiation, suggesting that elevated IL-21 in IgG4-RD contributes to Th17 polarization and overlap syndrome progression." (PMID 41181091, 2025).
IL21 also shares sentences with these, for which no sentence is quoted: multiple myeloma (6 papers); fungal infections (5); non-small cell lung carcinoma (5); chronic periodontitis (4); non-Hodgkin lymphoma (4); renal carcinoma (4); adenocarcinoma (2); anaplastic large cell lymphoma (2); atopic dermatitis (2); benign tumor (2); encephalitis (2); glomerulonephritis (2); head and neck cancer (2); Leukopenia (2); lumbar disc herniation (2); Lymphadenopathy (2); metastatic colorectal cancer (2); pemphigus vulgaris (2); primary biliary cholangitis (2); psoriatic arthritis (2); skin cancer (2); steatosis (2); Waldenstrom macroglobulinemia (2); acute-on-chronic liver failure (1); adult T cell leukemia (1); aggressive (1); airway hyperresponsiveness (1); Airway obstruction (1); antiphospholipid syndrome (1); Anxiety (1).
A further 84 diseases each share a sentence with IL21 in 1 paper.